POLR2A (RNA polymerase II subunit A)
Diseases named in the same sentence as POLR2A in open-access papers (continued):
Sharing a sentence is not in itself a finding about the gene and the disease.
ependymoma (2 papers, 2022). A WHO grade II, slow growing tumor of children and young adults, usually located intraventricularly. "This is the first report describing an ependymoma as an associated feature of the neurodevelopmental syndrome caused by a germline POLR2A variant." (PMID 35689525, 2022). "The eventual inclusion of the POLR2A neurodevelopmental disorder among the cancer predisposition syndromes with possible development of ependymomas is to be considered, although additional evidence is required due to the limited number of patients thus far reported with germline POLR2A variants." (PMID 35689525, 2022). "The presence of ependymoma as an additional feature, however, expands the awareness about genotype–phenotype correlation regarding POLR2A variants, adding new knowledge to both the phenotypic spectrum of POLR2A variants and the genetic etiology of ependymomas." (PMID 35689525, 2022). "Further information is required to explore the possibility of a differential clinical and functional impact of the pathogenic POLR2A variants and the eventual inclusion of the POLR2A neurodevelopmental disorder among the cancer predisposition syndromes with the possible development of ependymomas." (PMID 35689525, 2022). "Gait ataxia and other signs or symptoms attributable to hydrocephalus may help in the diagnostic workup aiming to detect patients with ependymoma‐associated POLR2A variants since obstructive hydrocephalus is present in up to 90% of patients with posterior fossa tumors at diagnosis." (PMID 35689525, 2022). "To date, ependymoma has never been reported in patients harboring pathogenic POLR2A variants." (PMID 35689525, 2022).
heart failure (2 papers, 2010 to 2021). Inability of the heart to pump blood at an adequate rate to meet tissue metabolic requirements. "In the condition of post-infarction heart failure, Polr2a was the better reference gene." (PMID 34496746, 2021).
hepatocellular carcinoma (2 papers, 2013 to 2026). A malignant tumor that arises from hepatocytes. "Additionally, in hepatocellular carcinoma (HCC), a dominant m.2356C>G clone correlated with POLR2A activation and widespread transcriptional amplification, consistent with a mitochondria-nucleus signaling axis contributing to adverse prognosis in this cancer type." (PMID 41727571, 2026).
non-small cell lung carcinoma (2 papers, 2021 to 2025). A group of at least three distinct histological types of lung cancer, including non-small cell squamous cell carcinoma, adenocarcinoma, and large cell carcinoma. "Besides, studies had reported that POLR2A gene polymorphism was associated with lower survival outcomes in patients with non-small cell lung cancer." (PMID 34899822, 2021).
Werner syndrome (2 papers, 2019 to 2021). "Studies have shown that, the expression of POLR2A was significantly lower expressed in normal elderly and Werner syndrome patients compared with young donor cells, suggesting that POLR2A may be involved in regulating cell senescence." (PMID 34899822, 2021). "Furthermore, it has been reported that POLR2A is significantly down-regulated in Werner syndrome patients or old human donor cells compared with young donor cells based on microarray analysis, indicating a role in cellular senescence." (PMID 31216022, 2019). "In addition, expression of POLR2A is significantly decreased in Werner syndrome patients or old human donor cells compared with young donor cells, also implying a role in cellular senescence." (PMID 31216022, 2019).
Anxiety (1 paper, 2020). Intense feelings of nervousness, tension, or panic often arise in response to interpersonal stresses. "Additionally, Polr2a expression is decreased in the dentate gyrus of the hippocampus alongside increased anxiety-like behavior following induced glucocorticoid receptor overexpression." (PMID 32416732, 2020).
asthma (1 paper, 2023). "Among the eight TFs, EZH2 and POLR2A have been associated with the pathogenesis of asthma." (PMID 37569643, 2023).
benign meningioma (1 paper, 2022). A grade I, slowly growing meningioma. "As somatic events, POLR2A mutations represent a recurrent somatic lesion in benign meningiomas." (PMID 35689525, 2022).
choriocarcinoma (1 paper, 2017). An aggressive malignant tumor arising from trophoblastic cells. "Interestingly, among the non-seminoma GCTs, the maximum amount of full-length ERVWE1 RNA (404% of POLR2A) was detected in the mixed GCT T43 consisting of 40% choriocarcinoma, 30% embryonal carcinoma and 30% yolk sac tumor components." (PMID 28302141, 2017).
colon cancers (1 paper, 2018).
colorectal tumors (1 paper, 2020). "Mice xenografted with cell lines that were POLR2A+/- developed colorectal tumors, however tumor growth was significantly suppressed by i.p. injection of antibody-coupled α-AMA." (PMID 32397434, 2020).
COVID-19 (1 paper, 2023). A disease caused by infection with severe acute respiratory syndrome coronavirus 2. "Our results have shown that POLR2A gene is overexpressed and up-regulated in patients with severe COVID-19 condition." (PMID 37347079, 2023).
endometrial carcinoma (1 paper, 2017). A malignant tumor arising from the epithelium that lines the cavity of the uterine body. "On the other hand, the analyzed samples of endometrial carcinomas and lymphomas displayed a significantly lower level of full-length ERVWE1 RNA (median 1 and 10% of POLR2A, respectively) than the seminomas." (PMID 28302141, 2017).
endometrial tumors (1 paper, 2014). "In that investigation 38 endometrial tumors and associated normal specimens were examined using qPCR, followed by GeNorm and NormFinder algorithms, that found HPRT1, POLR2A and PPIA as the most stable reference genes." (PMID 25473950, 2014).
Heat Stroke (1 paper, 2017). A condition caused by the failure of body to dissipate heat in an excessively hot environment or during PHYSICAL EXERTION in a hot environment. "When those four validated reference genes, SDHA, POLR2A, IPO8 and HMBS, were used for normalization, increased cerebral expressions of AQP4, CLDN5, OCLN, ZO1 and MMP9 were detected in heat stroke group." (PMID 28490769, 2017).
Hodgkins lymphoma (1 paper, 2017). A heterogeneous group of malignant lymphoid neoplasms of B-cell origin characterized histologically by the presence of Hodgkin and Reed-Sternberg (HRS) cells in the vast majority of cases. "The levels of ERVFRDE1 RNA in Hodgkin and non-Hodgkin lymphomas were similar, but the levels of spliced syncytin-2 mRNA were higher in the non-Hodgkin lymphomas (median 12% of POLR2A) than in the Hodgkin lymphomas (median 6% of POLR2A)." (PMID 28302141, 2017).
Hypotonia (1 paper, 2022). Hypotonia is an abnormally low muscle tone (the amount of tension or resistance to movement in a muscle). "Recently, POLR2A was implicated in an emerging neurodevelopmental disorder abbreviated NEDHIB (Neurodevelopmental Disorder with Hypotonia and Variable Intellectual and Behavioral Abnormalities) (OMIM # 618603)." (PMID 35328024, 2022). "Emerging evidence suggests that de novo POLR2A variants cause a newly described phenotype called ‘Neurodevelopmental Disorder with Hypotonia and Variable Intellectual and Behavioral Abnormalities’ (NEDHIB)." (PMID 35328024, 2022).
influenza infection (1 paper, 2024). "During influenza infection in the absence of the IFN-α/ß receptor, inflammatory and apoptotic responses may be initiated via induction of Ing1, Nr4a1, Polr2a, or Hoxa13." (PMID 38902760, 2024).
Kawasaki disease (1 paper, 2024). A rare inflammatory disease characterized by an acute febrile, systemic, self-limiting, medium-vessel vasculitis primarily affecting children. "POLR2A is upregulated in Kawasaki disease patients and may be associated with coronary artery abnormalities." (PMID 39090590, 2024).
kidney cancer (1 paper, 2019). Primary or metastatic malignant neoplasm involving the kidney. "ARNT, CTCF, POLR2A, RAD21 and REST were downregulated in kidney cancer samples and indicated poor prognosis when lowly expressed, which revealed that ARNT, CTCF, POLR2A, RAD21 and REST tended to be risk factors with lower gene expression." (PMID 31727869, 2019).
kidney failure (1 paper, 2021). An acute or chronic condition that is characterized by the inability of the kidneys to adequately filter the blood. "The implications of POLR2A and other dysregulated genes correlated with creatinine levels in cross-talks between LEAD and kidney failure onsets should be a subject of further studies." (PMID 33801150, 2021).
malignant mesothelioma (1 paper, 2013). A malignant neoplasm of the pleura or peritoneum, arising from mesothelial cells. "The present study revealed that in contrast to this ErbB2-Herceptin axis, YS110 treatment abundantly augments nuclear localization of CD26, and consequently suppresses POLR2A expression, leading to inhibition of malignant mesothelioma cell growth." (PMID 23638030, 2013). "Therefore, we examined the pattern of expression of POLR2A in tumor sections from patients with malignant mesothelioma, and in JMN and MSTO/CD26 cells, by immunohistochemical analysis." (PMID 23638030, 2013). "Therefore POLR2A appears to be functional in malignant mesothelioma cells." (PMID 23638030, 2013).
Meningothelial Meningioma (1 paper, 2021). A WHO grade I meningioma characterized by the presence of tumor cells that form lobules. "The proportion of meningothelial meningiomas harboring AKT1, KLF4, SMO, or POLR2A mutations was significantly high." (PMID 33772057, 2021).
myeloma (1 paper, 2024).
myocardial infarction (1 paper, 2011). Gross necrosis of the myocardium, as a result of interruption of the blood supply to the area, as in coronary thrombosis. "We found that Gapdh, Polr2a and Actb display high expression variability in mouse myocardial infarction tissues and that loss of statistical power and increase in sample size are the evident consequences of choosing suboptimal combinations of reference genes." (PMID 21858224, 2011). "We furthermore caution against the use of Gapdh, Polr2a, Actb, B2m and Eef1a1 for gene expression normalization in myocardial infarction studies because of selective up- or downregulation after myocardial infarction." (PMID 21858224, 2011). "Gapdh, Polr2a and Actb consistently showed the highest gene expression variability and the expression levels of Gapdh, Polr2a, Actb, B2m and Eef1a1 were found to be selectively up- or downregulated after myocardial infarction." (PMID 21858224, 2011). "We furthermore caution against the use of Gapdh, Polr2a, Actb, B2m and Eef1a1 for gene expression normalization in myocardial infarction studies because of selective up- or downregulation after myocardial infarction, which could potentially lead to biased study outcomes." (PMID 21858224, 2011).
prostate carcinoma (1 paper, 2025). A carcinoma that arises from epithelial cells of the prostate gland. "Supporting the relevance of this mechanism, TCGA prostate cancer data show an inverse correlation between RBX1 and POLR2A expression (R = −0.45), suggesting that the loss of POLR2A in cells with deletion of the 17p chromosomal region may be functionally compensated by RBX1 upregulation." (PMID 41487511, 2025).
pulmonary fibrosis (1 paper, 2022). Chronic progressive interstitial lung disorder characterized by the replacement of the lung tissue by connective tissue, leading to progressive dyspnea, respiratory failure, or right heart failure. "Taken together, we propose that Hprt, Polr2a and Sdha form a reliable set of reference genes for RT-qPCR in the bleomycin model of pulmonary fibrosis." (PMID 36251700, 2022). "Thus we suggest that Sdha, Polr2a and Hprt would form the best combination of reference genes for assessing bleomycin-induced pulmonary fibrosis at the 4-week time point." (PMID 36251700, 2022).
seminoma (1 paper, 2017). A radiosensitive malignant germ cell tumor found in the testis (especially undescended), and extragonadal sites (anterior mediastinum and pineal gland). "Median of the ERVWE1 expression in seminomas was higher than in the seminoma cell line TCam-2 (9% of POLR2A) and was comparable with BeWo cells (24% of POLR2A), the fusogenic cell line of choriocarcinoma origin." (PMID 28302141, 2017). "We observed significantly increased levels of full-length ERVWE1 RNA in seminomas with median 20% of POLR2A in comparison with seminoma-matched controls (4% of POLR2A) and non-seminoma GCTs (3% of POLR2A)." (PMID 28302141, 2017). "We detected a very high level of syncytin-1 mRNA in seminomas (median 49% of POLR2A), BeWo cells (80% of POLR2A), and particularly placenta (median 820% of POLR2A)." (PMID 28302141, 2017). "The level of full-length ERVFRDE1 RNA in seminomas, placentas, TCam-2 and BeWo cells was low (median 3, 4, 5 and 4% of POLR2A, respectively), but significantly higher than in seminoma-matched controls and, importantly, non-seminoma GCTs (1.5 and 1.2% of POLR2A, respectively)." (PMID 28302141, 2017). "In contrast to ERVWE1, the levels of spliced syncytin-2 mRNA in seminomas were not elevated over the seminoma-matched controls (median 11% POLR2A)." (PMID 28302141, 2017). "The level of syncytin-1 mRNA in seminomas was significantly higher than in the seminoma-matched controls (5% of POLR2A) and non-seminoma GCTs (2% of POLR2A)." (PMID 28302141, 2017). "ERVWE1 full-length RNA levels in the non-seminomas were comparable with non-seminoma-matched controls (2% of POLR2A), but higher than in the non-GCT testes (1% of POLR2A)." (PMID 28302141, 2017). "In the panel of randomly selected seminomas and non-seminoma GCTs, we detected similarly low levels of GCM1 expression (median 0.3350% POLR2A and 0.7493% POLR2A, respectively) that was not increased over the tumor-matched controls and non-GCT testes." (PMID 28302141, 2017). "Similarly to ERVWE1, the levels of spliced syncytin-2 mRNA in seminomas (median 12% of POLR2A) were higher than in non-seminoma GCTs (median 7% of POLR2A) and the non-GCT controls (median 5% of POLR2A)." (PMID 28302141, 2017).
Stroke (1 paper, 2026). Sudden impairment of blood flow to a part of the brain due to occlusion or rupture of an artery to the brain. "While stroke, inflammation, and hypoxia are known to broadly affect transcriptional activity, we found no specific reports indicating that PPIB or POLR2A are directly regulated under these conditions in the human brain." (PMID 41602576, 2026).
cancer (54 papers, 2011 to 2026). A tumor composed of atypical neoplastic, often pleomorphic cells that invade other tissues. "Collectively, these findings reinforce the central importance of POLR2A in transcriptional regulation and highlight its therapeutic vulnerability, particularly in cancers with 17p deletions or POLR2A mutations." (PMID 41487511, 2025). "In a recent study, α-amanitin was reported to show high cytotoxic activity in cancer cells hemizygous for the deletion of one allele of POLR2A, the gene encoding hRBP1, one of the subunits of RNA polymerase II." (PMID 34685458, 2021). "RNA polymerase II subunit A (POLR2A) is the largest subunit encoding RNA polymerase II and closely related to cancer progression." (PMID 34899822, 2021). "Further mutations in cancer-related genes included Nav3 (V1129L), Cenpf (D1327E), Muc5ac (A429P), Mpp7 (Q158R), Gas1 (G326R), Maged2 (A473S), Dusp1 (C24R), Ros1 (W1875C), Polr2a (M1102I), Rragd (L385P), and Hoxa9 (insertion of “G” in UTR)." (PMID 32793490, 2020). "For cancer related genes, Nav3, Cenpf, Muc5Ac, Mpp7, Gas1, MageD2, Dusp1, Ros, Polr2a, Rragd, Ros1, and Hoxa9 are mutated." (PMID 32793490, 2020). "Since RNA polymerase II mediates the transcription of all protein-coding genes in eukaryotic cells, POLR2A, as the catalytic subunit of it, was frequently detected to acquire mutations in cancers, suggesting its important roles in the cancer development." (PMID 29765536, 2018). "Several studies have specifically implicated POLR2A-associated lncRNAs in cancer." (PMID 41487511, 2025). "Likewise, POLR2A overexpression has been associated with tumor progression and a poor prognosis in several cancer types." (PMID 37888480, 2023). "A second study revealed that many cancers might be vulnerable to treatment with RNAPII inhibitors due to hemizygous loss of the POLR2A gene encoding RPB1." (PMID 32397434, 2020). "Taken together, these results demonstrate that POLR2A/RPB1 is broadly dysregulated across cancers, with considerable variability between tumor types." (PMID 41487511, 2025). "This mini-review summarizes current knowledge on the role of POLR2A/RPB1 in cancer biology, emphasizing its function as a central Pol II subunit." (PMID 41487511, 2025). "We evaluated the estimations using multiple functional assays associated with enhancers, including POLR2A ChIA-PET, STARR-seq, PRO-seq etc., and demonstrated that the modeling process improves the functional interpretation of SE activity in cancers." (PMID 38335222, 2024). "It was previously reported that the functional blockade of one of the subunits of RNA polymerase II, POLR2A, by RNAi strategies and treatment with chemical compounds such as α-amanitin resulted in growth inhibition of cancer cells." (PMID 31398954, 2019).